MCL1 (MCL1 apoptosis regulator, BCL2 family member)
Diseases named in the same sentence as MCL1 in open-access papers (continued):
Sharing a sentence is not in itself a finding about the gene and the disease.
diffuse large B-cell lymphoma (30 papers, 2014 to 2025). "BCL-2 and functionally redundant counterpart, MCL-1, are frequently over-expressed in high-risk diffuse large B-cell lymphoma (DLBCL)." (PMID 29269870, 2017). "Overexpression of Mcl-1 was also predisposed these transgenic mouse model to late-onset of B-cell lymphoma with a spectrum of histological subtypes including follicular lymphoma and diffuse large B-cell lymphoma." (PMID 34336857, 2021). "We have demonstrated that AZ5576, a selective CDK9-inhibitor, led to rapid downmodulation of MYC and Mcl-1 in diffuse large B-cell lymphoma (DBLCL), accompanied by a shutdown of the MYC transcriptional program and apoptosis." (PMID 36998071, 2023). "Increased abundance of anti-apoptotic BCL-2, BCL-XL or MCL-1 is found in several B-cell malignancies, including diffuse large B-cell lymphoma (DLBCL), thereby counteracting pro-apoptotic signaling induced by oncogenic stress." (PMID 37684238, 2023). "S63845 binds with high affinity specifically to the BH3-binding groove of MCL-1 inducing downstream apoptosis signaling and has shown pre-clinical anti-tumor activity in different malignancies such as rhabdomyosarcoma, diffuse large B-cell lymphoma and AML." (PMID 35031695, 2022). "Nevertheless, the tumor types in this model differ from those developed in mice harboring a human MCL-1 minigene, which displayed tumors resembling follicular lymphoma and diffuse large B-cell lymphoma." (PMID 34336857, 2021). "One report has presented evidence that USP9x can promote tumor cell survival through stabilization of the pro-survival BCL2 family member MCL1 in human follicular lymphomas and diffuse large B-cell lymphoma and multiple myleomas." (PMID 27462448, 2016). "When CFZ is combined with obatoclax, a pan-BH3 mimetic that inhibits Mcl-1, enhanced apoptosis is observed in diffuse large B-cell lymphoma cell lines." (PMID 25612802, 2014). "CKD-581 treatment also up-regulated the phosphorylation of histone H2AX (γH2AX, DNA double-strand break marker), and reduced levels of MYC and anti-apoptotic proteins such as BCL-2, BCL-6, BCL-XL, and MCL-1 in DH/DE-diffuse large B cell lymphoma (DLBCL) cell lines." (PMID 32575557, 2020). "This is exemplified by diffuse large B-cell lymphoma (DLBCL) where MCL-1 contributes to intrinsic and acquired resistance to the rationally designed polyselective BCL-2, BCL-XL, and BCL-W inhibitor ABT-737 and the monoselective BCL-2 inhibitor ABT-199." (PMID 31692812, 2019). "In Diffuse Large B-cell Lymphoma (DLBCL), elevated anti-apoptotic BCL2-family proteins (e.g., MCL1, BCL2, BCLXL) and NF-κB subunits (RelA, RelB, cRel) confer poor prognosis." (PMID 40819126, 2025). "In line with our findings in ALL, a recent study also found heterogeneous sensitivity of diffuse large B-cell lymphoma cells to inhibitors of BCL-2, BCL-XL and MCL-1." (PMID 35031695, 2022). "AZD4573 could downregulate multiple oncoproteins (MYC, Mcl-1, JunB, PIM3) and deregulate PI3K pathways in diffuse large B-cell lymphoma (DLBCL)." (PMID 38566153, 2024). "Furthermore, Gel-BLyS was shown to lead to downregulation of interleukin-6 receptor, a protein that is highly expressed in diffuse large B cell lymphoma (DLBCL) and impacts the STAT3 targets c-Myc, p21, Mcl-1, and Bcl-xL." (PMID 35744957, 2022). "Diffuse Large B-Cell Lymphoma (DLBCL) DOHH2 and SU-DHL-16 cells, which have high Mcl-1 protein levels and are resistant to ABT-199, showed high sensitivity to dinaciclib + ABT-199, a combination that was highly synergistic (CI<0.2)." (PMID 26219338, 2015).
lung adenocarcinoma (30 papers, 2005 to 2025). A carcinoma that arises from the lung and is characterized by the presence of malignant glandular epithelial cells. "Frequency of Mcl1 gain has been shown to be high in NSCLCs and its inhibition has been associated with suppression of tumor growth in mouse models of lung adenocarcinoma." (PMID 34359807, 2021). "Since M. tb infection induces COX-2 production and COX-2 has been linked to regulation of Mcl-1 production in human lung adenocarcinoma cells, we first determined if COX-2 is important for PPARγ activity and the production of Mcl-1 during M. tb infection of human macrophages." (PMID 29928066, 2018). "Among the hotspot amplifications were the regions encompassing EGFR (ch7p11),KRAS (ch12p12), and MCL1 (ch1q21), which are well-recognized cancer drivers that play crucial roles and are known to be amplified in lung adenocarcinoma." (PMID 40867048, 2025). "The results showed that the mRNA expression levels of ESR1, DDX3X, MAPK10, KIT, FOXO1, and MCL1 were significantly lower in both lung adenocarcinoma (LUAD) and lung squamous cell carcinoma (LUSC) tissues (p < 0.001) than normal lung tissues." (PMID 38180107, 2023). "In summary, our results indicate that the RUNX2 transcription factor participates in the intrinsic pathway of apoptosis avoidance through the transcriptional regulation of antiapoptotic genes BCL2, BCL-XL, and MCL1 in lung adenocarcinoma." (PMID 36510562, 2022). "In a comparison of adenocarcinomas of the lung, Mcl-1 turned out to secure its survival and to be critical for its development." (PMID 35887198, 2022). "S63845 induced cytotoxicity in lung adenocarcinoma cell lines is positively correlated with MCL-1 protein expression, which delays tumor progression and reduces tumor size in mouse." (PMID 33883020, 2021). "Our results support the critical role of the Oct4/Stat1/Mcl-1 axis in cell survival in lung adenocarcinoma." (PMID 34685622, 2021). "Our data demonstrated that tumor tissues from lung adenocarcinoma patients are characterized by the presence of the putative biomarkers for the response to Mcl-1 inhibition (i.e., high expression of Bak and low expression of Bcl-xL)." (PMID 35008345, 2021). "The utility of targeting MCL-1 alone in solid tumours was recently demonstrated in lung adenocarcinoma where deletion of Mcl1 restricted tumour development and treatment with S63845 shown to delay tumour progression in vivo." (PMID 33785871, 2021). "In our study, we demonstrated that the stem cell marker Oct4 is overexpressed and, ultimately, results in an anti-apoptosis phenotype through the Stat1/Mcl-1 axis in lung adenocarcinoma." (PMID 34685622, 2021). "To estimate the possible utility of BH3 mimetics targeting Mcl-1 for the treatment of solid cancers, we performed the analysis of mRNA expression and protein levels in lung adenocarcinoma tissues." (PMID 35008345, 2021). "HSP90 inhibitor-induced MCL1 downregulation correlated with sensitivity in a panel of nine mesothelioma and seven lung adenocarcinoma cell lines." (PMID 26096930, 2016). "Consistent with other studies, we found that DLBCL has the highest percentage of BCL2 amplification (11 %) and lung adenocarcinoma has the highest percentage of MCL1 amplification (20 %)." (PMID 26134786, 2015). "Based on this model system, Pemetrexed-mediated increase in Noxa resulted in suppression of Usp9X and subsequent depletion of Mcl-1 protein levels, rendering lung adenocarcinoma cells more sensitive to apoptotic stimuli." (PMID 26008975, 2015). "In contrast, the anti-proliferative activity of MCL-1 and BCL-2 is associated with a favorable prognosis effect in some early carcinomas, such as lung adenocarcinoma." (PMID 21401964, 2011). "Human lung adenocarcinoma cells, exposed to NSAIDs showed an effective reduction of the antiapoptosis Bcl-2 family member Mcl-1." (PMID 15812552, 2005).
lung adenocarcinoma (continued). "Taken together, we demonstrate that Oct4 is a pro-survival factor by inducing Stat1 expression and that the Oct4/Stat1/Mcl-1 axis may be a potential therapeutic target for lung adenocarcinoma." (PMID 34685622, 2021). "Such expression patterns are similar to those in S63845-sensitive cell lines, and thus suggest that Mcl-1 inhibition might be the rational in lung adenocarcinoma patients." (PMID 35008345, 2021). "Previously, we observed that KRIBB11 decreases MCL-1 expression in A549 lung adenocarcinoma cells." (PMID 34299435, 2021). "Finally, we evaluated the survival rate of patients with lung adenocarcinoma from the TCGA dataset, depending on the expression levels of Bak, Bcl-xL and Mcl-1." (PMID 35008345, 2021). "Furthermore, in a mouse lung adenocarcinoma model, Mcl-1 overexpression was shown to help tumor progression by inhibiting Myc-induced apoptosis." (PMID 32260280, 2020). "Copy number analysis of TCGA tumor samples in cBioportal database showed that both USP13 and MCL1 were genomically amplified in a wide range of cancer types, in particular a considerable proportion of lung adenocarcinoma, lung squamous cell carcinoma and ovarian serous carcinoma cases." (PMID 29335437, 2018). "Although the precise mechanism of this phenomenon is not clear, these data suggest that the Bak/Bcl-xL/Mcl-1 axis might play an important role in the response of lung adenocarcinoma to treatment and risk stratification of patients." (PMID 35008345, 2021). "IGROV-1 (human ovarian carcinoma cells), H522 (lung adenocarcinoma cells), and SF-268 (human glioblastoma cells) responded to JEV infection, with a substantial fall in MCL-1 synthesis." (PMID 38256213, 2024). "Despite data that Mcl-1 expression does not correlate with response to Mcl-1 inhibition, in lung adenocarcinoma patients Mcl-1 expression can be additional risk stratification factor which might help identifying patients with worse prognosis who would benefit more from Mcl-1 inhibition." (PMID 35008345, 2021). "In the TCGA dataset of lung adenocarcinoma, expression of MCL1, BCL2, BCL2L2, and BCL2A1 was significantly higher in non-tumor relative to tumor cells." (PMID 39122703, 2024). "However, in contrast to lung adenocarcinoma cells in which Bim appears to play the major role in the synergized apoptosis, XIAP, Mcl-1 and Bim all contributed to the synergized apoptosis in RCC cells." (PMID 23387989, 2013). "Indomethacin, however, did not decrease expression of Bcl-2, Bcl-XS/L or Mcl-1 in GLC4 or GLC4-Adr which is in contrast to results described for lung adenocarcinoma cell lines." (PMID 15812552, 2005). "Compound 5 showed moderate cytotoxic activity against human colorectal adeno-carcinoma (HT-29) and lung adenocarcinoma epithelial (A549) cell lines, with IC50 values in the range 15–17 μM, and compounds 3, 6 and 9 exhibited weak binding affinity for the anti-apoptotic protein Mcl-1." (PMID 24492595, 2014). "Higher Mcl-1 expression and PI were observed in NSCLC compared with non-cancerous lung tissues (non-CLT), while AI was significantly lower in lung adenocarcinoma (ADC) compared with non-CLT." (PMID 31601252, 2019).
mantle cell lymphoma (30 papers, 2014 to 2025). Mantle cell lymphoma is a rare form of malignant non-Hodgkin lymphoma affecting B lymphocytes in the lymph nodes in a region called the ``mantle zone''. "On the other hand, mimicking in vivo environment during in vitro investigations in CLL and mantle cell lymphoma cells also showed Mcl-1, Bcl-XL, and survivin as primary determinants of ibrutinib and venetoclax resistance." (PMID 35273915, 2022). "Similar results were observed in the case of Jeko-1 and NCEB mantle cell lymphoma cells in which bortezomib alone clearly up-regulated MCL-1 expression, and this effect was attenuated by HHT." (PMID 30445933, 2018). "Bcl‐2 and Mcl‐1 are antiapoptotic proteins that are also commonly overexpressed in mantle cell lymphoma." (PMID 30065968, 2018). "We then used these lipidoid nanoparticles to examine the effect of silencing a trio of genes—Cyclin D1, Bcl‐2, and Mcl‐1—on mantle cell lymphoma apoptosis and proliferation rates." (PMID 30065968, 2018). "Gene-deletion studies have demonstrated that the expression of Mcl-1 is critical to survival and has been shown to correlate with high-grade follicular lymphomas, mantle cell lymphoma and DLBCL, predominately the ABC subtype." (PMID 24788952, 2014). "MCL-1 knockdown triggers spontaneous apoptosis in several mantle cell lymphoma cell lines." (PMID 33883020, 2021). "Mantle cell lymphomas with elevated expression of Mcl‐1 are often associated with high grade morphology and increased proliferation, while benign mantle zone B‐cells are Mcl‐1 negative." (PMID 30065968, 2018). "In several cancer cell lines, including multiple myeloma (MM) and mantle cell lymphoma (MCL), treatment with bortezomib resulted in NF-κB pathway inhibition, cleavage of Mcl-1 and prompted c-Jun/AP-1 pathway." (PMID 37176148, 2023). "In AML, CLL, and mantle cell lymphoma, upregulation and reliance on BCLX and MCL1 were reported to account for venetoclax resistance." (PMID 38893249, 2024). "Although the mechanism is not fully understood, the overexpression of MCL-1 and BCL-xL, in mantle cell lymphoma and CLL, is thought to mediate this resistance." (PMID 37601693, 2023). "In mantle cell lymphoma cells it was shown that VEN sensitivity was impaired via NF-kB pathway upregulation, leading to over-expression of MCL-1 and BCL-XL and thus mediating VEN resistance." (PMID 35778418, 2022). "In two different mantle cell lymphoma cell lines, one normal cell line (JeKo-1) and one invasive cell line (MAVER-1), silencing MCL-1 induced a dose-dependent increase in the proportion of apoptotic cells." (PMID 33883020, 2021). "In another hematological neoplasm, mantle cell lymphoma (MCL), casein kinase 2 (CK2) has been shown to be over-expressed, and targeting CK2 reduces MCL-1 levels, which in turn sensitizes MCL cells to BCL-2-specific venetoclax inhibitor and presents a novel therapeutic strategy for MCL patients." (PMID 38256213, 2024).
oral cancer (29 papers, 2012 to 2025). "Our study provides evidence that the concurrent expression of EGFR and Mcl-1 is linked to a poor prognosis in oral cancer patients." (PMID 38888847, 2025). "Taken together, the consistent findings of Mcl-1 overexpression in cancers indicates its association with carcinogenesis, and it is suggested that Mcl-1 has a significant impact on the development and progression of oral cancer." (PMID 35524332, 2022). "The aim of the current review was to evaluate the expression, regulation, function, associated features, and potential therapeutic agents of Mcl-1 in oral cancers." (PMID 35524332, 2022). "Determining the associations between Mcl-1 and the various categories and stages of oral cancer can enhance our understanding of its potential impact on the clinical progression of the disease." (PMID 35524332, 2022). "Overexpression of Mcl-1 is associated with the poor prognosis and cisplatin-resistance in oral cancer, thus representing a promising target for cancer therapy." (PMID 33114727, 2020). "We have previously reported overexpression of antiapoptotic MCL-1 protein in human oral cancers and its association with therapy resistance and poor prognosis, implying it to be a potential therapeutic target." (PMID 28947954, 2017). "We also demonstrated predominant overexpression of antiapoptotic MCL-1 protein in oral cancer tissues versus normal and its association with therapy resistance and poor prognosis in oral cancer patients." (PMID 28947954, 2017). "In the present study, the correlation of Mcl-1 isoforms and clinicopathological parameters of oral cancer patients, revealed significant association of Mcl-1L splice variant with advanced tumor size (p = 0.013) and lymph node positivity (p = 0.021)." (PMID 25409302, 2014). "This is the first study that demonstrates expression of the three Mcl-1 splice variants in oral cancer cell lines & tumor tissues." (PMID 25409302, 2014). "Our study for the first time assessed Mcl-1 splice variants in oral cancer and demonstrated, anti-apoptotic Mcl-1L isoform to be a chemoresistance and prognostic factor and a potential therapeutic target in oral cancers." (PMID 25409302, 2014). "The present study was undertaken to elucidate the expression profile of Mcl-1 isoforms in oral cell lines and a large cohort of tumors, which demonstrated the association of anti-apoptotic Mcl-1L expression with prognosis in oral cancer." (PMID 25409302, 2014). "We have also demonstrated high PCNA and Mcl-1 protein expression to be associated with poor prognosis in oral cancer patients treated with definitive radiotherapy." (PMID 25409302, 2014). "Our group has previously shown that Mcl-1 is overexpressed in oral cancer and is closely associated with poor clinical outcomes, suggesting that the inhibition of Mcl-1 might be a good strategy for the treatment of oral cancer." (PMID 38888847, 2025). "As a testimony of the prognostic potential of the Mcl-1 transcript variants, we have demonstrated that the antiapoptotic Mcl-1 long isoform transcript variant was particularly overexpressed in oral cancers and was also associated with poor prognosis and chemoresistance." (PMID 36045907, 2022). "Furthermore, Mcl-1 overexpression is also associated with acquired radioresistance in cancer cells, including in oral cancer cells as shown in our studies." (PMID 36045907, 2022). "Oral cancer is linked with apoptotic proteins such as Bcl-xl, Bcl-2 and Mcl-1." (PMID 32994681, 2020). "However, we and others have reported the association of MCL-1 overexpression with resistance to radiation and cisplatin in oral cancers." (PMID 28947954, 2017). "Therefore, in the present study we wanted to investigate the association of Mcl-1 isoforms with radioresistance of oral cancer cells using siRNA strategy." (PMID 22873792, 2012).